MIR4258 (microRNA 4258)
Synonyms: hsa-mir-4258
Gene: MicroRNA gene on chromosome 1 (154,975,693 to 154,975,783, forward strand). Ensembl gene ENSG00000264349.
Homologues: Orthologues: chimpanzee MIR4258 (100% identical).